CXCL12 (C-X-C motif chemokine ligand 12)
Diseases named in the same sentence as CXCL12 in open-access papers (continued):
Sharing a sentence is not in itself a finding about the gene and the disease.
tumor (continued). "Moreover, in an organotypic tumor spheroid-immune cell co-culture model inhibition of CXCL12 enhanced T cell recruitment and the anti-PD-1 immunotherapy response in a colon carcinoma cell model." (PMID 30873179, 2019). "VIC-008 monotherapy showed limited effects on tumor mass control and CXCL12 expression." (PMID 31320999, 2019). "CAFs-secreted CXCL12 drives tumor progression and metastasis through two possible mechanisms." (PMID 31705019, 2019). "However, it is worth considering our results in light of recent studies showing that targeting CXCL12 that is expressed in tumor stroma synergizes with anti-PD-L1 immunotherapy." (PMID 31694242, 2019). "We also tested whether medium and low cell binding ADCs 553 and 556 were able to compete with CXCL12 for binding to CXCR4 in CXCR4Low tumours." (PMID 30792442, 2019). "Moreover, these MSCs release VEGF for neo-vascularization in the TME and produce CXCL12 to support tumor cell growth and survival." (PMID 30927930, 2019). "In addition, the interaction between fibroblast-derived C-X-C motif chemokine ligand 12 (CXCL12, SDF1) and endothelial cells was recently reported to enhance tumor cell intravasation by increasing vascular permeability." (PMID 31683635, 2019). "On the other hand, the synthesis of CXCL12 by stroma cells may support tumor progression by autocrine and paracrine mechanisms." (PMID 30012106, 2018). "MSC may facilitate extravasation of tumor cells, which is known to be partly mediated through secreted chemokines (i.e., C-X-C motif chemokine 12 (CXCL12))." (PMID 29494553, 2018). "CXCL12 modulates the tumor microenvironment by autocrine and paracrine secretion." (PMID 30105558, 2018). "In silico analysis confirmed that the expression of CXCR4 in the primary tumor significantly correlated not only with the expression of its ligand CXCL12 (Spearman's coefficient, rs = 0.4920) but also with the expression of VIM (rs = 0.4779) and CD163 (rs = 0.4853)." (PMID 29849822, 2018). "All these studies support the hypothesis that specific CXCL12 chemokines/CXCR4 receptor signaling may play important roles in NB tumor cell invasion and metastasis." (PMID 30149659, 2018). "VEGF and CXCL12 are master regulators of neoangiogenesis that drives tumor development." (PMID 30622662, 2018). "Although the cellular source of CXCL12 levels could be highly diverse, secretion of CXCL12 by CXCL12 positive tumor cells may account for higher serum concentrations of CXCL12." (PMID 30012106, 2018). "The ability of CXCL12 and MYC to promote cell migration by increasing glycolytic flux may also explain why CXCL12/CXCR452 and MYC53 are associated with increased tumor invasiveness and poor survival." (PMID 30202007, 2018). "In addition, CXCL12 modulates the immune response to the tumor tissue, e.g., by recruiting dendritic cell populations." (PMID 30105558, 2018). "Previous work demonstrated that radiation induces tumor invasiveness by increasing tumor-derived CXCL12 at the invasive tumor border, which may enhance the potential for CXCR4 signaling." (PMID 30451884, 2018). "High SDF-1/CXCL12 expression in tumours aids in the capture of CXCR4-expressing monocytes." (PMID 30504836, 2018). "In addition, bone marrow-derived CXCR4+ vascular cells can be recruited by CXCL12-expressing tumor/stromal cells and contribute to a microenvironment that supports tumor angiogenesis." (PMID 29554149, 2018). "One way tumor cells home to and colonize bone is via the CXCL12/CXCR4 signaling axis." (PMID 29865211, 2018). "Moreover, mononuclear phagocytes are attracted to tumor and metastatic sites by the presence of CXCL12, which is able to shape monocyte polarization toward a protumor M2-like phenotype." (PMID 29849822, 2018). "Indeed, DAPT-mediated Notch inhibition causes a decrease in tumor cells growth and migration through the downregulation of CXCR4 and CXCL12 expression." (PMID 30154786, 2018). "CXCR4 and CXCL12 play a pivotal role in tumor development and metastasis." (PMID 30105558, 2018).
tumor (continued). "Other examples of paracrine signalling that is deregulated by CAFs include the secretion of chemokine CXCL12 with subsequent tumour growth facilitation and the expression of intra-cellular and extracellular Ca2+-binding protein S100A4 with subsequent tumour progression and metastatic spread." (PMID 29362402, 2018). "Collectively, our study does not indicate an exclusive role for CXCL12 in promoting both mDia2 loss and tumor migration." (PMID 29596520, 2018). "We next crossed Il7-Cre mice with Cxcl12fl/fl mice and found that cell type-specific genetic ablation of Cxcl12 expression substantially reduced the frequency of tumor-initiating cells (1 in 4,809 control vs. 1 in 44,814 Il7-Cre Cxcl12fl/fl) without affecting the time to engraftment." (PMID 29632733, 2018). "Interestingly, the expression of MMPs, and in particular the release of pro-MMP-9, is promoted by tumor-derived CXCL12 in an autocrine fashion." (PMID 30591657, 2018). "Hence, it is possible that early tumor cell-fibroblastic stromal cell interactions dependent on the CXCL12/CXCR4 pathway govern tumor propagation from few malignant cells under both primary and metastatic conditions." (PMID 29632733, 2018). "Moreover, CXCR4 and CXCL12 tumor expression significantly contribute to serum CXCL12 concentrations." (PMID 30012106, 2018). "CXCR4 and CXCL12 were expressed mainly in S100-positive tumor cells and not in tumor-associated macrophages." (PMID 29515781, 2018). "The ability of MYC and CXCL12/CXCR4 signaling to maintain a high glycolytic flux may also allow tumor cells to invade tissues with low-oxygen tension." (PMID 30202007, 2018). "Furthermore, increasing evidence suggests that myofibroblasts stimulate tumor progression through CXCL12 secretion." (PMID 30380719, 2018). "These functional differences may be due to the Src-status of the tumor cells, which mediates responses to CXCL12 produced by the bone microenvironment." (PMID 29642534, 2018). "Tumor associated macrophages (TAM) are also a source of CXCL9 and CXCL12." (PMID 30319638, 2018). "Bone metastatic tumor cells may also be selected for in the primary tumor, in which stromal-derived CXCL12 selects for clones that are able to home to and survive in the CXCL12-rich region of the bone marrow." (PMID 29642534, 2018). "Much of the Chemokines such as CXCL12 expressed by tumor organoids may induce this migration, although it is possible that effects of tumor organoids on degradation of the extracellular protein matrix may contribute to this observation." (PMID 29587663, 2018). "Among HER2-overexpressing cats, there was a significant difference in OS and DFS curves between the positive and negative CXCL12 tumor expression groups, with CXCL12 negative PT associated with unfavorable prognosis." (PMID 30012106, 2018). "The epidermal growth factor receptor (EFGR) mutation was closely related to the invasion and metastasis of lung adenocarcinoma and the biological axis of CXCR4/CXCL12 (chemokine receptor 4/chemokine ligand 12) played an important role in the organ-specific metastasis of the tumor." (PMID 30037369, 2018). "It is also reported that CCL2 and CXCL12 synergistically enhance the in vitro migration of human monocytes and macrophages, suggesting that expression of multiple chemokines in the tumor microenvironment is required for the efficient recruitment of monocytes and TAMs." (PMID 30483271, 2018). "The role of CXCL12/CXCR4 signaling in tumor cell motility and invasion is well established." (PMID 29930538, 2018). "In addition, high expression of CXCR4 in tumor cells correlated with lymph node metastasis and with high expression of CXCL12 in tumor-harboring lymph nodes." (PMID 30257500, 2018).
tumor (continued). "In recent years, the alarmin HMGB1, which can be massively released within the tumor microenvironment, has also been described to form a complex with the chemokine CXCL12 enhancing CXCR4-mediated signaling, thus providing an additional regulation of the activity of the chemokine system." (PMID 30319638, 2018). "Additionally, the CXCR4/CXCL12 axis is a volatile system, part of a large network of the extracellular matrix/tumor cell microenvironment with high spatiotemporal differences." (PMID 30191351, 2018). "Accordingly, inhibition of CXCR7 function may serve to increase the clinical efficacy of CXCR4 inhibitors such as AMD3100, as blockage of CXCR4 only partially inhibits tumor cell response to CXCL12 gradients in multiple animal models." (PMID 28055968, 2017). "However, CXCR4 knockdown attenuated the effect of CXCL12 on enhancing tumor spheroid formation in HBx-expressing OV6+ CSCs." (PMID 28102846, 2017). "CXCL12 gradients in the tumor microenvironment are isoform dependent; isoforms with higher ECM binding affinity more easily form gradients directed into the tissue, whereas isoforms with lower ECM binding affinity more easily form gradients directed toward the vasculature." (PMID 29117251, 2017). "However, we found that for a given tumor cellular composition, the gradient is unable to switch directions because the two competing sources of CXCL12, the blood and the secretion rate from cells in the tumor, vary in unison." (PMID 29117251, 2017). "Interestingly, a study evaluated the role of SDF-1a/CXCL12 in the migration of MSCs in response to tumor cells elucidating that Jak/STAT, MEK/ERK as well as NFkB pathways are activated downstream of SDF-1." (PMID 29069870, 2017). "We developed a computational model to simulate CXCL12 gradients in a tumor." (PMID 29117251, 2017). "The ability of CAFs to influence tumor growth was partly dependent on their ability to induce angiogenesis by CAF-derived SDF-1 (also known as CXCL12) and recruitment of bone marrow-derived endothelial cells or by CAF-derived PDGF-C, a member of the PDGF family or secreting proangiogenic factors." (PMID 28178651, 2017). "In particular, CXCR4 stimulation was found to induce expression of vascular endothelial growth factor (VEGF) in human breast carcinoma cells and conversely blockade of CXCL12/CXCR4 signalling was able to suppress tumour angiogenesis and tumour growth in vivo in a murine model." (PMID 28332618, 2017). "Finally, to test the possible therapeutic utility of pharmacologic inhibition of the Cxcl12/Cxcr4 axis on antral tumor development, we treated Mist1-CreERT; Cxcr4-EGFP; Apcflox/flox mice with AMD3100, a specific inhibitor of CXCR4." (PMID 29340033, 2017). "Specifically, proinflammatory cytokine IL-6 induces Twist1 expression in normal fibroblasts via STAT3 phosphorylation, and Twist1 then promotes the transdifferentiation of normal fibroblasts to CAFs via activation of a strong tumor-promoting chemokine, CXCL12, as well as suppression of senescence." (PMID 29029429, 2017). "Variable CXCR4 levels between testis tumor samples suggested responsiveness to CXCL12 may differ between individuals." (PMID 29250030, 2017). "Also, cancer cells and cancer-associated stromal cells showed down-regulation of miR-126, thus enhancing the release of CXCL12 and subsequently recruiting MSCs to further promote tumor cell invasion and metastasis." (PMID 28423491, 2017). "Furthermore, through encapsulation of chemotherapeutic drug doxorubicin (Dox) into M-E5, we found that M-E5 was capable of sensitizing tumor cells for Dox in vitro via blocking CXCR4/CXCL12 axis." (PMID 28793338, 2017).
tumor (continued). "Activation of Cxcl12/Cxcr4 signaling appears to be needed for antral tumor growth." (PMID 29340033, 2017). "In conclusion, miR-137 serves as a tumor suppressor by inhibition of CXCL12 in human GBM." (PMID 29254162, 2017). "In these conditions, CXCR4 causes tumor cell trafficking and homing into lymphoid and non-lymphoid tissues where CXCL12 is produced." (PMID 29387053, 2017). "How does CXCL12 gene silencing impact tumor initiation and/or progression?" (PMID 28418886, 2017). "Perhaps CXCL12 induces murine stromal cells to generate new vessels in a paracrine effect and may be a good objective for targeted therapy to reduce tumour growth." (PMID 28386296, 2017). "Indeed, primarily in ER-positive invasive ductal cancer, we observed significant upregulation of COUP-TFI and CXCR4 and downregulation of CXCR7 and CXCL12, and the levels of these changes showed correlations with tumor grade." (PMID 28666461, 2017). "Furthermore, the expression of CXCL12 protein was found to be significantly higher in tumors than that in non-tumor tissues (p<0.01)." (PMID 29254162, 2017). "Furthermore, CXCL12 can attract CXCR4-positive immune cells or fibroblasts to the tumor sites to assist in tumor development." (PMID 28566721, 2017). "As the key contributor in tumour microenvironment, CAFs secrete a number of factors such as cytokines, chemokines (e.g. IL-6, CXCL12), growth factors (e.g. HGF, transforming growth factor β, fibroblast growth factor) and receptors (e.g. platelet-derived growth factor receptor)." (PMID 28258248, 2017). "However, the expression of mRNA and protein of CXCL12 had much higher expression in tumor tissues than those in paired normal tissues." (PMID 29254162, 2017). "Interestingly, the PT-induced upregulation of ICAM-1, VCAM-1 and CXCL12 were dispensable for the PT-evoked tumor cell adhesion." (PMID 29100413, 2017). "Additionally, neoplastic cells coexpressed chemokines (CXCL9, CXCL10, GRO, and CXCL12) and their receptors in both tumours." (PMID 28386296, 2017). "ACKR3 can also influence tumor vascularization by regulating CXCL12 levels." (PMID 29156704, 2017). "In order to determine the mechanism by which fibrocytes were recruited into the tumor environment, we performed human-specific gene profiling using tumor tissues, and found that C–X–C motif chemokine ligand 12 (CXCL12), the ligand of CXCR4, played a role in the recruitment of fibrocytes." (PMID 29286323, 2017). "CXCL12/CXCR4 signaling axis regulates the process of tumor proliferation and metastasis." (PMID 28489887, 2017). "CXCL12 plays a pivotal in different stages of tumor development and cancer metastasis." (PMID 28929029, 2017). "High expression of CXCL12/CXCR4 was observed in all passages of both tumours and in the neovascularisation experiment, this could be related with their aggressive clinical behaviour." (PMID 28386296, 2017). "In addition, another NF-κB pathway, which is initiated by ligands such as RANKL, LTα, LTβ and LIGHT produced by TAMs, targets tumor-promoting genes like CXCL12 and VEGFC via receptors such as LTβR, CD40 and RANK." (PMID 28467800, 2017). "CXCL12 and CXCR4 are always expressed at significantly increased levels in gastrointestinal cancers, which is associated with the activation of downstream pathways and survival, proliferation, angiogenesis, and migration of tumor cells." (PMID 28544785, 2017). "As most chemokines, CXCL12 and its receptor may serve as connecting bridges between cancer and stromal cells, thus creating a permissive microenvironment for tumor growth and invasion." (PMID 29240722, 2017). "Chemokine receptor 4 (CXCR4) and its chemokine ligand 12 (CXCL12) have been identified with significantly elevated levels in various malignancies including GC, which correlates with the survival, proliferation, angiogenesis, and metastasis of tumor cells." (PMID 28544785, 2017). "For example, we found that CXCL12 and JAK1 are both more highly expressed in low risk tumours." (PMID 27469239, 2016).
tumor (continued). "In addition, the frequency of increased concentrations was the highest for CXCL12 with CXCR4 levels in combination (94%) and improved the diagnostic sensitivity of combined measurement of classical tumor markers—CEA with SCC-Ag (33%)." (PMID 27041792, 2016). "Furthermore, CCL5 and CXCL12 levels in the brain tissues of mice with grade 3 tumours were higher than in those with grade 2 and 1 tumours." (PMID 27417157, 2016). "CXCL12/CXCR4 axis plays a crucial role in determining the homing of metastatic tumor cells with poor prognosis, which the expression of CXCR4 and Bcl-2 and PI3K/Akt and ERK1/2 signaling are controlled and the level at which it is expressed mark the difference between normal and pathological events." (PMID 27668882, 2016). "Furthermore, we detected CXCR4 expression on 4T1 TDLN B cells, and 4T1 tumor cells produced its ligand CXCL12." (PMID 27528023, 2016). "The number of attached tumor cells gradually increased with CXCL12 concentration." (PMID 27191997, 2016). "SDF-1 (also known as CXCL12) is involved in angiogenesis and direct tumor growth." (PMID 26828520, 2016). "Next, we investigated whether A2BR-induced CXCL12 expression could contribute to the tumor promoting effects of Bay60-6583 in vivo." (PMID 27590504, 2016). "Our in vitro experiments demonstrated that IL-2 modulated expression of CD25 on B cells after activation /expansion (A/E) before adoptive transfer; enhanced CXCR4 expression on B cells; augmented CXCL12 production by 4T1 tumor cells, and increased production of perforin by B cells." (PMID 27528023, 2016). "Within the tumor tissue, distinct stromal cells express CXCL12 and it may be mainly secreted by stromal fibroblasts in tumor tissue." (PMID 26880981, 2016). "To establish whether CXCR4 sustained tumor metastatic properties in a Cxcl12-dependent manner, we first assessed whether the CXCR4-CXCL12 axis acts across zebrafish and human." (PMID 26744352, 2016). "The chemokine CXCL12 (C-X-C chemokine ligand 12) and its ligand CXCR4 (C-X-C chemokine receptor type 4) are involved in the development of several organs, including the kidney, and are also associated with tumor growth and metastasis." (PMID 27830498, 2016). "In addition, CXCL12 can protect tumor cells from apoptosis induced by chemotherapeutic drugs activating antiapoptotic pathways and modulating the attachment of cancer cells through the regulation of integrins." (PMID 26880981, 2016). "Moreover, these aberrant MSC release VEGF for neo-vascularization within the TME and they produce CXCL12 (=SDF1 (stromal cell-derived factor 1)) to support tumor cell growth and survival." (PMID 27608835, 2016). "In addition, western blotting revealed that CCL5 and CXCL12 protein levels were significantly higher in the brain tissues of mice that developed tumours after ESC or iPSC transplantation (P < 0.05)." (PMID 27417157, 2016). "Additionally, CXCL12 promotes tumor progression by recruitment of endothelial and hematopoietic progenitor cells to the tumor microenvironment, where they support vasculogenesis." (PMID 27835905, 2016). "The CXCL12/CXCR4 pair is indeed involved in the increased survival and/or proliferation of cancer cells from various types including virus-related cancers, as well as in the promotion of tumor metastasis and angiogenesis linked to tumor progression." (PMID 27918748, 2016). "The CXCR4-CXCL12 axis is necessary for mediating the attraction of monocytic MDSCs into the tumor environment and PGE2 is important to regulation of CXCL12 production in cancer-associated fibroblasts and the cancer environment, and to enhancement of CXCR4 expression in Mo-MDSCs." (PMID 26758420, 2016). "CXCL12 regulates tumor growth, angiogenesis and progression by acting on CXCR4-expressing cells." (PMID 27590504, 2016).